ADAM17 (ADAM metallopeptidase domain 17)
Diseases named in the same sentence as ADAM17 in open-access papers (continued):
Sharing a sentence is not in itself a finding about the gene and the disease.
COVID-19 (continued). "This is implied that COVID-19-induced lung-destructive inflammation might erupt rather via aggravation of ADAM-17-mediated release of mACE2 and TNF-α which results in the dysregulation of local RAS in favor of Ang II/AT1R axis and promoting inflammatory responses." (PMID 36851081, 2023). "No causal effect for the cytoplasmic domain of ADAM17 on COVID-19 was observed." (PMID 37958866, 2023). "However, the affirmation of this statement through population studies remains constrained as there is limited evidence indicating whether ADAM17 levels can serve as prognostic indicators for severe COVID-19 outcomes." (PMID 37958866, 2023). "Unfortunately, precise fat distribution in our patients is not available, yet the sex-specific changes observed could reflect the higher prevalence of visceral obesity in men and be in line with ADAM17 playing a role in the crosstalk of visceral obesity with COVID-19 severity." (PMID 36009555, 2022). "However, the regulatory effects of CD, TQ, and m62A on ADAM17 expression and their potential anti-COVID-19 mechanisms remain unclear." (PMID 36558177, 2022). "Thus, it can be assumed that increased ADAM17 cleavage activity on ACE2 would result in increased circulating Angiotensin II levels that may contribute to the vascular pathophysiology of COVID-19 and to renal and other systemic complications." (PMID 36009555, 2022). "In addition, ADAM17 is involved in the Notch signaling pathway, which plays an important role in the differentiation and activation of innate and adaptive immune cells and is therefore crucial for the cytokine storm formation in patients with severe COVID-19." (PMID 35163504, 2022). "We hypothesized that blockade of ADAM17 activity would alter COVID-19 pathogenesis." (PMID 35757773, 2022). "Hence, developing a selective inhibitor of ADAM-17 for COVID-19 patients with CRS may be a promising strategy to alleviate inflammatory responses." (PMID 33628091, 2021). "On the other hand, ADAM17 cellular activity has been shown to be positively regulated by epidermal growth factor receptor (EGFR) signalling, thus raising the question of the impact of anti-EGFR tyrosine kinase inhibitors (TKI) on COVID-19 susceptibility through ADAM17 down-tuning." (PMID 33531686, 2021). "Two ADAM17 inhibitors have been tested in animal models of COVID-19, apratastat (TMI-005) and TMI-1, resulting in a significant reduction in the production of pro-inflammatory cytokines as well as in protective effects against lung injury associated with COVID-19." (PMID 34685735, 2021). "Upregulation of ADAM-17 may therefore potentially exacerbate vascular dysfunction in COVID-19." (PMID 33380345, 2020). "The relevance of ADAM17-mediated ACE2 cleavage and release (shedding) in COVID-19 pathophysiology is underscored by the correlation between elevated circulating ACE2 levels and disease severity." (PMID 40431631, 2025). "An impaired interferon response to COVID-19 predicts severe disease, and it has been proposed that at least IFN-gamma can suppress ADAM-17 activity." (PMID 38892098, 2024). "There are indications that the interaction between ADAM-17 activity and the SARS-CoV-2 receptor ACE2 plays a crucial part in the progression to severe COVID-19." (PMID 38892098, 2024). "In fact, similar to that of ADAM17 mRNA levels, the increase in IFITM3 mRNA levels found in PBCs of COVID-19 patients was greater the higher the severity observed in the ultimate course of the disease, and maximal in patients with obesity (BMI > 30)." (PMID 36009555, 2022). "Gene expression levels of ADAM17 and IFITM3 were increased in PBCs of COVID-19 patients compared with control subjects (by 63% and 700%, respectively)." (PMID 36009555, 2022). "mRNA levels of ADAM17, IFITM3, IL6, CXCL10, CXCL11, IFNG and TYK2 were increased in PBCs of COVID-19 patients (n = 73) compared with controls (n = 47), independently of sex." (PMID 36009555, 2022).
COVID-19 (continued). "We suggest that the increased expression of both ADAM17 and IFITM3 plays an important role in the boosted pathogenesis of COVID-19 in male patients with obesity." (PMID 36009555, 2022). "In the context of COVID-19, some targets of interest that are activated by furin are IFN-γ and ADAM17." (PMID 35982454, 2022). "AAT acts as an inhibitor of inflammatory molecules (e.g., IL-8, TNF-α) and of proteases involved in the pathophysiology of COVID-19 (e.g., elastase, TMPRSS2 and ADAM17)." (PMID 35163482, 2022). "These events lead to further activation of ADAM17, amplifying the inflammatory response and likely setting the stage for the cytokine storm and ARDS seen in some COVID-19 patients." (PMID 35757773, 2022). "Protease–antiprotease imbalances can arise during the clinical course of COVID-19 infection and recent studies have demonstrated that AAT can bind and inhibit key proteases involved in the pathophysiology of COVID-19, including TMPRSS2 and ADAM17." (PMID 35269582, 2022). "Our results clearly demonstrate the importance of ADAM17 in SARS-CoV-2 induced disease in mice and likely in COVID-19 in humans." (PMID 35757773, 2022). "A last natural strategy in the context of scenario 2 to reduce ACE2 overactivity, responsible for the exacerbated inflammatory responses in COVID-19, is to target ACE2 shedding via the inhibition of ADAM17." (PMID 34685735, 2021). "After binding to ACE2 receptor the COVID-19/ACE2 complex generally takes entry to the host cell by endocytosis, those which are unable to take entry to host cell shed by ADAM Metallopeptidase Domain 17 (ADAM17)." (PMID 34833873, 2021). "I have already suggested that SARS-CoV-2 is able to induce shedding of the zinc-carboxypeptidase ACE2 by activating the zinc-metalloprotease ADAM17, finally leading to systemic upregulation of ACE2 activity in COVID-19 patients." (PMID 33673459, 2021). "ADAM17 induces the shedding of ACE2 and increases circulatory ACE2 (sACE2), thereby mitigating further entry of COVID-19." (PMID 33153216, 2020). "The evidence presented in this review highlights the deleterious effect of ACE2 downmodulation by ADAM17 and TMPRSS2 in COVID-19 pathogenesis." (PMID 33117379, 2020). "Therefore, over-activation of ADAM17 and TMPRSS2 could be the main mechanism underlying the negative effects of RAS imbalance, acute inflammation and intravascular coagulation observed in elderly males with COVID-19 comorbidities." (PMID 33117379, 2020). "Studies have shown that SARS-CoV viruses activate ADAM17, thus explaining increased plasma levels of ACE2 observed in patients with SARS and COVID-19." (PMID 32635289, 2020). "For TMPRSS2, IL-17A, ADAM-17, and AP, values were significantly higher in all non-healthy groups (previously infected, mild, and severe COVID-19) compared to healthy individuals." (PMID 40003732, 2025). "ADAM-17, another key regulator in cellular processes, has been shown to increase in the upper respiratory tract, where it modulates the release of soluble ACE2 (sACE2) and stimulates Th17 immune responses, further contributing to inflammation in COVID-19." (PMID 40003732, 2025). "While anti-ADAM17 compounds can upregulate mACE2 expression, increasing viral binding to ACE2-positive cells, they can inhibit systemic ACE2 release in the early phase of COVID-19, reducing sACE2 and suppressing viral infectivity." (PMID 38652364, 2024). "We primarily searched for the articles from the timeframe of 2003 to 2023 within medical databases, including PubMed, Scopus and Web of Science using the following keywords: coagulation, COVID-19, SARS-CoV-2, RAAS, angiotensin, ADAM17, pathophysiology and inflammation." (PMID 38652364, 2024). "Hospitalization due to COVID-19 was also identified as having a marginal negative effect on circulating ADAM17 levels (extracellular domain, coefficient = −0.02, 95% CI −0.04–0, IVW method)." (PMID 37958866, 2023).
COVID-19 (continued). "Next, we explored how the expression of ACE2, ADAM17 and CTSL in specific cell subsets correlated with three key clinical features (age, sex, and cardiovascular comorbidities) that might make COVID-19 more severe." (PMID 37259108, 2023). "Inhibition of ADAM17/MMP with a small molecule inhibitor also reduced lung injury in a non-infectious inflammatory model related to COVID-19 in mice." (PMID 35757773, 2022). "Interestingly, the expression pattern of ADAM17, IFITM3 and IFNE in PBCs was related to both the severity of COVID-19 evolution and obesity status, especially in the male patients." (PMID 36009555, 2022). "The ‘prevalent’ ‘candidate genes’ (ADAM10, ADAM17, AKT1, CTNNB1, ESR1, FGFR1, PIK3CA) might have the most prominent pathophysiological relevance in COVID-19." (PMID 36229517, 2022). "We hypothesize that interplay of ACE2/ADAM17/TMPRSS2 and CD146 in the kidney may lead to sex differences in CKD as well as in COVID-19 by their sex differential expression and pathways." (PMID 35887687, 2022). "The effect of ADAM17 on cancer patients infected with COVID-19 and its correlation with immune cell infiltration have not been fully elucidated." (PMID 35720350, 2022). "Both rs4622692:T>G and rs1048610:T>C (p.S608S) of ADAM17 had not been reported elsewhere concerning COVID-19." (PMID 36292769, 2022). "Similarly, use of an enhancer of ADAM-17, a metalloproteinase involved in the shedding of ACE2, can potentially work as a drug for the treatment of COVID-19." (PMID 33918318, 2021). "Moreover, CsA was reported as able to augment Ang II-stimulated rise in intracellular free calcium in vascular smooth muscle cells and to increase ADAM17 activity up to three-fold, likely leading to an ACE2 shedding increase detrimental to COVID-19 patients." (PMID 34552938, 2021). "ADAM17 is responsible for delivering the soluble forms of TNF, TNFR1, and TNFR2; we hypothesized COVID-19 patients had increased ADAM17, explaining why TNFRs levels increased." (PMID 34445140, 2021). "The enzyme activity of ADAM17 is inhibited and regulated by TIMP3, but SARS-CoV-2 reduces TIMP3 mRNA expression in alveolar epithelial cells, that likely promotes greater ADAM17 activity in COVID-19 patients." (PMID 32664949, 2020). "Therefore, in this review, we focus on the main pathophysiological aspects of ACE2, ADAM17, and TMPRSS2 host proteins in COVID-19." (PMID 33117379, 2020). "Additionally, we discuss a possible mechanism to explain the deleterious effect of ADAM17 and TMPRSS2 over-activation in the COVID-19 outcome." (PMID 33117379, 2020). "ADAM17 is also expressed within the renal tubules, and its activation, mediated by classical RAAS activation, may prevent the COVID-19 shed by sACE2 from entering tubular cells." (PMID 33153216, 2020). "In this study, we monitored the levels of ACE2, TMPRSS2, IL-17A, ADAM-17, VD, and AP in NPS, serum, and saliva to assess their impact on health status, further supporting the need for multi-biomarker approaches in evaluating COVID-19’s effects on the immune system." (PMID 40003732, 2025). "However, clinical studies in humans on the potential benefit of selective ADAM-17 inhibition on COVID-19 are lacking." (PMID 38892098, 2024). "However, critical COVID-19 seemed to have a marginal negative effect on circulating ADAM17 levels (extracellular domain, coefficient = −0.01, 95% CI: −0.02–0, IVW method)." (PMID 37958866, 2023). "Altogether, it is implied that the rise in sACE2 in COVID-19 is the result, not the cause, of SARS-CoV-2-induced activation of a cascade of proinflammatory pathways accompanied by ADAM-17 stimulation which lead to the release of mACE2 as a soluble form into the circulation." (PMID 36851081, 2023). "Moreover, ADAM17-mediated processing of ACE2 in response to the virus can decrease cellular levels of functional receptor, thereby deregulating the renin-angiotensin system with detrimental effects on the outcome of COVID-19 patients." (PMID 33579029, 2021).
COVID-19 (continued). "Indeed, overactive ADAM17 with excessive shedding of MerTK and ACE-2 could comprise a significant pathogenetic mechanism of COVID-19 and ME/CFS." (PMID 34248502, 2021). "In a kind of positive feedback loop, the ADAM17-mediated shedding activity appears to be enhanced by the binding of the viral spike protein to ACE2, and to be stimulated by AngII and the pro-inflammatory cytokines interleukin (IL)-1β and TNF-α, whose secretion is elevated in COVID-19 patients." (PMID 34685735, 2021). "In this context, a key factor to understand this apparent paradox in the pathophysiology of COVID-19, related to the conflicting evidences ACE2’s role, could be found in the delicate interplay balance between the cleavage of ACE2 by both ADAM17 and TMPRSS2 proteases in a stepwise fashion." (PMID 33117379, 2020). "There are currently no reports on the functional roles of ACE2/ADAM17/TMPRSS2 and CD146 in sex differences of disease, neither on CDK nor on COVID-19." (PMID 35887687, 2022). "Indeed, inhibiting ACE2 or the metalloprotease ADAM17 that is responsible for ACE2 shedding could be an effective way to block the overactivation of the RAS axes, which in turn would lead to the suppression of the inflammatory responses in COVID-19 and attenuate severe lung injury." (PMID 34685735, 2021). "COVID-19/ACE2 complexes enter host cells through endocytosis, and those that are not endocytosed are shed by ADAM17." (PMID 33153216, 2020). "If ADAM17 expression is not downregulated by SIRT1, TNF-α and IL-6 are released, resulting in an uncontrolled hyperinflammatory response as may happen with COVID-19." (PMID 35458574, 2022). "Again, like results for ADAM17, a correlation between BMI and IFITM3 gene expression in PBCs was found in the COVID-19 patients, but not in the controls, and it was stronger and of higher statistical significance when only the male patients were considered in the linear regression model." (PMID 36009555, 2022). "Active VD targeting of ADAM17 and consequently, the attenuation of ACE2-cleavage to maintain its protective pathways, may not be able to fully answer the questions regarding COVID-19 protection." (PMID 34444716, 2021). "Notably, differential ACE2 cleavage mediated by ADAM17/TMPRSS2 may have a significant impact on the pathophysiology of COVID-19, since TMPRSS2-mediated ACE2 cleavage does not enhance ACE2 shedding from the cell surface, inhibiting the shedding process mediated by ADAM17." (PMID 40431631, 2025). "Furthermore, considering that TIM3 is cleaved in both ADAM17 and a disintegrin and metalloproteinase domain-containing protein 10 (ADAM10), we measured ADAM10 (transcriptional level), but our data showed that ADAM10 was not increased in any of the COVID-19 patient groups." (PMID 34445140, 2021).
hepatocellular carcinoma (44 papers, 2014 to 2025). A malignant tumor that arises from hepatocytes. "The EGFR/PI3K/AKT signaling pathway has been proven to be associated with the ADAM17-mediated cisplatin resistance of hepatocellular carcinoma cells." (PMID 27313893, 2016). "MiR-122 has also been characterized as a tumor suppressor miRNA affecting hepatocellular carcinoma intrahepatic metastasis by angiogenesis suppression, and its mode of action has been associated with the regulation of the disintegrin and metalloprotease 17 (ADAM17)." (PMID 29027980, 2017). "In another study, miR-3163 has been identified as a tumor suppressor in hepatocellular carcinoma (HCC) through inhibition of ADAM metalloprotease domain-17 (ADAM17), leading to decreased activation of the Notch signaling pathway." (PMID 40396180, 2025). "In both hepatocellular carcinoma and ovarian cancer, treatment with cisplatin leads to ADAM17-dependent release of cleaved growth factors and subsequent activation of the EGFR/PI3K/AKT pathway." (PMID 39506058, 2024). "ADAM17 enhances cell migration and invasion in hepatocellular carcinoma by modulating the integrin β1 pathway." (PMID 39346916, 2024). "In hepatocellular carcinoma cells, ADAM17 plays a role in hypoxia-induced drug resistance by activating the EGFR/PI3K/Akt pathway." (PMID 39346916, 2024). "To assess a possible involvement of ADAM17, we silenced it in human hepatoma cells and assessed HCV infectivity." (PMID 37967063, 2023). "In hepatocellular carcinoma cells, miR-122 and miR-3163 upregulation can suppress ADAM17 levels, thereby inhibiting cell proliferation and enhancing sensitivity to antitumor drugs." (PMID 37175410, 2023). "A previous study reported that several GPCRs, including GPR50, are involved in the reprogramming of somatic cells to BCSCs, suggesting that GPR50 can act as a tumor suppressor in hepatocellular carcinoma (HCC) through the ADAM17-Notch signaling pathway." (PMID 36769125, 2023). "ADAM17 and Tspan8 are expressed in a multitude of cancers, including colorectal and hepatocellular carcinoma." (PMID 36078095, 2022). "Consistently, overexpression of ADAM17 in melanoma and hepatocellular carcinoma cells resulted in reduced apoptosis accompanied by a significant decrease in caspase-3 cleavage." (PMID 36293469, 2022). "Recently, ZLDI‐8 was reported as a novel ADAM‐17 inhibitor involved in enhanced chemotherapeutic effects of sorafenib in hepatocellular carcinoma cells." (PMID 33247998, 2021). "The upregulation of ADAM17 has been reported to be associated with invasion and metastasis in various tumors, however the molecular mechanism of ADAM17 in the progression of hepatocellular carcinoma (HCC) remain to be clarified." (PMID 33100908, 2020). "Our results confirm that ADAM17 plays a pivotal role in hepatocellular carcinoma invasion and migration." (PMID 33100908, 2020). "miR-122 is a tumor suppressor miRNA that negatively regulates ADAM17, resulting in the repression of hepatocellular carcinoma angiogenesis and metastasis." (PMID 26078057, 2015). "Indeed we and others demonstrated that cisplatin treatment leads to upregulation of ADAM17 and increased release of growth factors that mediate cisplatin resistance in ovarian cancer and hepatocellular carcinoma, respectively." (PMID 39506058, 2024). "Similarly, in another study, we noted that ADAM17 knockdown inhibited cell invasion and metastasis in hepatocellular carcinoma." (PMID 37175410, 2023). "In addition to ADAM9, ADAM10 and ADAM17 are also known to predict poor prognosis in hepatocellular carcinoma and lung cancer, based on previous studies." (PMID 35740916, 2022). "Moreover, ADAM17 expression in metastatic gastric cancer and hepatocellular carcinoma was upregulated." (PMID 33922533, 2021).